IL1B (interleukin 1 beta)
Diseases named in the same sentence as IL1B in open-access papers (continued):
Sharing a sentence is not in itself a finding about the gene and the disease.
Sepsis (continued). "Numerous studies have shown low HDL-C but high TG in inflammatory and autoimmune diseases, including sepsis, IBD, systemic lupus erythematosus, and rheumatoid arthritis, and cytokines like TNFα, IL-1β, and IL-6 are thought to be involved." (PMID 40484317, 2025). "Our previous study indicated that sepsis activates the mitochondria-dependent NLRP3 inflammasome pathway and increases the release of inflammatory cytokines such as IL-1β." (PMID 40575778, 2025). "In a CLP mouse model of sepsis, the system significantly reduced serum levels of inflammatory cytokines (TNF‐α, IL‐1β, and IL‐6), decreased mortality rates and protected against tissue damage." (PMID 40599085, 2025). "This meta-analysis demonstrated that ulinastatin significantly reduces mortality and inflammatory markers such as CRP, IL-1β, IL-6, IL-8, IL-10, PCT, and TNF-α in patients with sepsis compared to control group." (PMID 40667510, 2025). "In sepsis, microglia become hyperactivated, releasing large amounts of pro-inflammatory cytokines (TNF-α, IL-1β) and chemokines (MCP-1)." (PMID 40823184, 2025). "Uncontrolled inflammation in sepsis results in an increase in the release of pro-inflammatory cytokines, including tumor necrosis factor alpha (TNF-α), interleukin-1 beta (IL1-β), IL-6, and HMGB-1." (PMID 39838305, 2025). "The results showed that LPS injection significantly increased the levels of proinflammatory cytokines IL‐1β, IL‐6, and TNF‐α, confirming successful sepsis induction." (PMID 39836501, 2025). "Compared with the Sepsis group, the Cur + Sep group showed significantly lower Paller damage scores, reduced Scr, BUN, TNF‐α, IL‐1β, IL‐6, MDA, Fe2+ levels, and ACSL4 protein expression (all p < 0.05)." (PMID 41140036, 2025). "In the initial hit phase, the sepsis-induced systemic inflammatory response syndrome (SIRS) triggers a significant release of pro-inflammatory cytokines, particularly TNF-α, IL-1β, and IL-6." (PMID 41451099, 2025). "CSN6 upregulation increased IL-1β, IL-6, and TNF-α levels in an in vitro sepsis model (n = n = 6 per group)." (PMID 40595050, 2025). "In sepsis, accumulated bile acids act as DAMPs to activate the NLRP3 inflammasome-IL-1β axis, accompanied by the down-regulation of the FXR, forming a “cholestasis-inflammation-organ injury” vicious cycle." (PMID 41244772, 2025). "We observed prominent necroptosis activation in sepsis—evidenced by elevated RIPK-1, IL-1β, and IL-18 levels and suppressed caspase-8 levels." (PMID 40722817, 2025). "One study found that exosomes derived from sepsis patients’ blood can upregulate miR-885-5p in AC16 cells, downregulate homeobox containing 1 (HMBOX1) and increase IL-1β and IL-18, further promoting pyroptosis of AC16 cells." (PMID 40041174, 2025). "For example, IL-1β and IL-6 concentrations are higher in the hippocampus and serum of Sprague-Dawley male rats and C57BL/6 male mice with LPS-induced sepsis initiated during the dark compared to light phase." (PMID 39968295, 2025). "In pathological conditions, such as sepsis and ARDS, M1 macrophages contribute to alveolar barrier disruption by secreting TNF-α and IL-1β, which increase vascular permeability and promote leukocyte recruitment." (PMID 41488672, 2025). "Compared to the sham group, the levels of IL-6, IL-1β, IL-10 and TGF-β in the sepsis group and the placebo group were also significantly elevated (p < 0.01)." (PMID 41584453, 2025). "In the early stage of sepsis, cytokines like tumor necrosis factor (TNF), interleukin-1β (IL-1β), and interleukin-6 (IL-6) mediate the inflammatory reaction, initiating the systemic inflammatory response syndrome (SIRS)." (PMID 40129981, 2025). "The release of IL-4 and IL-10 in sepsis suppress Th1 inflammatory response by reducing IFN-γ, TNF-α and IL-1β secretion by Th1 cells and inhibit Th1 cells polarization." (PMID 40364841, 2025). "We next focused on proinflammatory cytokines that play a major role in sepsis, including IFN-γ, TNFα, IL-6, and IL-1β." (PMID 40510337, 2025).
Sepsis (continued). "Macrophages are recruited during sepsis, and release various inflammatory factors such as TNF, IL-1β and IL-6, along with chemokines like CCL6 and CD14, and the transcription factor NF-κB1." (PMID 40775729, 2025). "In previous reports, LPS induction exhibited an increase in cytokine levels (IL-1β, TNF-α and IL-8), activating the inflammatory pathway indicating sepsis." (PMID 41020892, 2025). "Notable candidates include MCC950, a selective NLRP3 inhibitor; anti–IL-1β monoclonal antibodies; and emerging GSDMD inhibitors, all of which aim to suppress the hyperinflammatory milieu of sepsis." (PMID 40558557, 2025). "THCQ reduces key inflammatory factors in sepsis, such as TNF-α, IL-1β, and IL-6, inhibits oxidative stress, and alleviates iron overload, indicating its multiple protective mechanisms in mitigating the inflammatory cascade of sepsis." (PMID 40963685, 2025). "Another study, which enrolled 3,250 subjects, found that serum concentrations of IL-1β, TNF-α, and interferon (IFN)-γ were elevated in patients with sepsis." (PMID 38558800, 2024). "A recent study demonstrated that sepsis-exos increased the level of miR-885-5p, decreased HMBOX1, elevated IL-1β and IL-18, and promoted pyroptosis in AC16 cells." (PMID 39770410, 2024). "Conversely, the expression levels of pro-apoptotic and pro-inflammatory markers Caspase-3, P2X7R, TLR4, IL-1β, and TNF-α were found to be significantly escalated in the CLP group, which was indicative of the potent inflammatory response triggered by sepsis." (PMID 38546748, 2024). "Administering a Pyr10 inhibitor to block TRPC3 channel alleviated the development of LPS-induced sepsis in mice by reducing the activation of several pro-inflammatory genes, including PTGS2, TNFA, IL-1B, and IL-6." (PMID 38731999, 2024). "In a CLP surgery-induced sepsis model of mice, the administration of 5–20 g/kg of the QX1 decoction reduced sepsis-induced upregulated levels of serum IFN-γ, IL-1β, IL-3, IL-6, IL-17, IL-4, IL-10 and TNF-α." (PMID 39051370, 2024). "Sepsis-induced inflammatory mediators, such as TNF-α, IL-6, and IL-1β, inhibited the protective anti-inflammatory cytokine IL-10." (PMID 38926458, 2024). "Pro-inflammatory cytokines, such as IL-1β, IL-6, and TNF-α, are markedly elevated in sepsis and contribute to widespread inflammation, tissue damage, and organ failure." (PMID 39205680, 2024). "The concentrations of IL-1β (p < 0.001), IL-6 (p < 0.001), and TNF-α (p < 0.001) were significantly elevated in the liver in the Tac1+/+ mice following CLP-surgery-induced sepsis compared with the sham-operated controls." (PMID 38539834, 2024). "This review will focus on IL-6, IL-1β, TNF-α, and IL-10 due to their well understood pathology in sepsis to further explore the shared pathophysiology of sepsis across both humans and horses." (PMID 39273060, 2024). "There is convincing evidence linking high serum levels of inflammatory cytokines, such as IL-6, IL-1β and TNF-α, with hypophosphatemia in patients with sepsis." (PMID 38787228, 2024). "We showed that pretreatment of septic mice with minocycline reduced IL‐1β and TNF‐α expression at 24 h post‐sepsis induction." (PMID 39370294, 2024). "Neutrophils isolated from sepsis patients (n=45) and healthy control donors (n=7) were examined for their response to a mix of proinflammatory cytokine (cytomix: TNF-α/IL-1β/IFN-γ) stimulation as compared to buffer-treated cells." (PMID 38524125, 2024). "Pro-inflammatory cytokines, including interleukin-1β (IL-1β), CCL4, CCL5, and CXCL10, have emerged as potential biomarkers with significant implications for diagnosing sepsis and assessing the severity of cytokine storms." (PMID 38496165, 2024). "On the other hand, during sepsis there is an acute release of multiple inflammatory mediators (TNF-α, IL-6, and IL-1β) which can lead to both tissue and organ damage, even contributing to cell death." (PMID 38474158, 2024).
Sepsis (continued). "Regarding neutrophils, the levels of Tnfα, IL-6, IL-1β, CXCL1, CXCL2, CCL5, and CXCL10 increased significantly in response to sepsis sEVs compared with those from the control group and healthy individuals." (PMID 38910259, 2024). "The results showed that the levels of Tnfα, IL-1β, CXCL2, CXCL10, CCL2, and CCL3 increased significantly in response to sepsis sEVs compared with healthy sEVs." (PMID 38910259, 2024). "The findings of our study are in agreement with the results of some others in this field, for example, it has been reported that in many inflammatory diseases such as sepsis, TNF-a, IL-1b and IL-6 serum levels increase significantly." (PMID 38952770, 2024). "Unsurprisingly, the levels of IL-1β, TNF-α, and IL-6 produced by TREM2+ monocytes were positively correlated with serum triglyceride concentrations of sepsis patients." (PMID 39405126, 2024). "Further research is required to assess the potential importance of molecular pathways in vagal IL-1B/TRPA1 signaling and their combined role in immune regulation during sepsis." (PMID 38731999, 2024). "This experimental model of sepsis demonstrates that LPS administration increases the expression of Chop, Bip/GRP78, IL-1β, and caspase-3 in the rat liver." (PMID 38353687, 2024). "We found positive correlation between expression of IL-1β and C3AR1 only in patients suffering from sepsis." (PMID 38236896, 2024). "Sepsis was demonstrated to upsurge the expression of NF-kB and repress Nrf-2 signaling pathway, which further stimulates the expression of TNF-α, IL-1β, and IL-6." (PMID 37548662, 2024). "Epalrestat, a commercial ARI, was employed as an intervention in a rat sepsis model, demonstrating significant reductions in inflammatory factors TNF-α, IL-1β and IL-6." (PMID 38188141, 2024). "In animal studies, acute sepsis increased S100A12 expression in serum and atrial tissues, correlating positively with inflammatory markers (IL-1β, IL-6, TNF-α) and negatively with heart rate, indicating a predisposition to AF." (PMID 39444551, 2024). "It has been reported that the serum levels of IL-1β and TNF-α in some sepsis patients are significantly increased, which is positively correlated with the inflammatory reaction and the severity of the disease (Zhen, Li & Wang, 2013)." (PMID 38646480, 2024). "As such, monoclonal antibodies targeting interleukin-1 beta (IL-1β) in the CANTOS trial resulted in lower cardiovascular events, however total mortality was unaffected due to severe leukopenia and subsequent sepsis." (PMID 38309122, 2024). "In the context of sepsis, NLRP3 functions by recruiting and activating caspase-1, leading to release of IL-1β and IL-18, initiating a cascade of inflammatory reactions that ultimately leads to substantial inflammation-induced damage and multi-organ failure." (PMID 39364223, 2024). "Significant elevations in serum cytokines, such as IL-1β, IL-6, TNF-α, IL-8, and the IL-7 family of cytokines, have been noted during sepsis." (PMID 39201339, 2024). "When compared to sham-operated mice (sham+vehicle), mice subjected to CLP-sepsis and treated with vehicle (CLP+vehicle) showed a significant increase in the serum levels of pro-inflammatory cytokines IL-1β, IL-6 and anti-inflammatory cytokine IL-10 (P<0.0001)." (PMID 39559354, 2024). "IL-1β, IL-6, and TNF-α are all potent proinflammatory cytokines that contribute heavily to organ dysfunction from sepsis." (PMID 38646937, 2024). "The cytokine profile analysis revealed that ghrelin and Fer-1 effectively normalized the expression of IL-6, IL-1β, TNF-α, and IL-22, which were dysregulated during sepsis, highlighting their anti-inflammatory properties." (PMID 39857660, 2024). "The results demonstrated that PBMCs from the sepsis group had significantly higher relative protein levels of NLRP3, caspase-1, cleaved GSDMD, and IL-1β than those from the control groups." (PMID 38169584, 2024).
Sepsis (continued). "In this study we show that CLP-sepsis increased the serum levels of the cytokine IL-1β, which is secondary (at least in part) to the activation of NLRP3 inflammasome during sepsis." (PMID 39559354, 2024). "During sepsis, dysregulated release of inflammatory cytokines such as tumor necrosis factor-alpha (TNF-α), interleukin-1 beta (IL-1β), interleukin-6 (IL-6), and interleukin-10 (IL-10) can contribute to harmful effects." (PMID 39597952, 2024). "In this study, our findings demonstrated that LBT Lobetyolin effectively protects mice from sepsis induced by LPS by downregulating the production of pro-inflammatory cytokines such as TNF-α, IL-6, and IL-1β in macrophages." (PMID 38799158, 2024). "In the CLP group, there was a significant elevation in both IL-1β and TNF-α levels compared to the control group, reflecting the pronounced inflammatory response induced by sepsis (p < 0.001)." (PMID 38326366, 2024). "Cmtm3 KO reduced the release of TNF-α, IL-1β, and IL-10 in the peripheral blood of CLP-induced sepsis mice, while TLR4 overexpression reversed this protective effect." (PMID 39455728, 2024). "In sepsis, inflammatory factors such as TNF-α and IL-1β stimulate hepatocytes, leading to oxidative stress and microcirculatory disorders, which promote the release of ALT and GGT." (PMID 39712312, 2024). "IL-1β, IL-6, and TNF-α are common inflammatory factors that reflect the body’s inflammation levels, changing in response to infections, sepsis, or other inflammatory triggers." (PMID 39247187, 2024). "The CLP-induced sepsis model was validated through overexpression of TNF-α, IL1-β, IL-6, and NF-kB, thereby demonstrating the occurrence of a systemic inflammatory response." (PMID 38629103, 2024). "In a mouse sepsis model, administration of GDF3 has demonstrated improvements in cardiac function, suppression of the inflammatory cytokine IL-1β, and a reduction in mortality." (PMID 38543054, 2024). "HMGB1 has been known to induce the production of cytokines like TNF-α, IL-1β, and IL-6 through various mechanisms, including the NF-κB and ERK 1/2 pathways, exacerbating the pathological condition of sepsis." (PMID 38474222, 2024). "Protection against severe sepsis was confirmed with the observation that TNF-α, IL-1β, IL-6, LDH, ALT and urea levels were decreased to almost basal levels in MFX-treated mice 24 h after CLP compared to untreated mice." (PMID 39200042, 2024). "Macrophages and neutrophils play crucial roles in the inflammatory response during sepsis, secreting inflammatory mediators such as TNF-α and IL-1β to enhance the inflammatory response." (PMID 39455728, 2024). "Specifically, our findings demonstrate that LBT exerts a significant inhibitory effect on lipopolysaccharide (LPS)-induced sepsis by suppressing the expression of key pro-inflammatory cytokines such as IL-6, TNF-α, and IL-1β." (PMID 38799158, 2024). "In our study, we observed a significant increase in NO levels and pro-inflammatory cytokines IL-1β, IL-6, and TNF-α in the serum of mice with CLP- and LPS-induced sepsis." (PMID 39337575, 2024). "We focused on six cytokines that play a major role in sepsis: IFN-γ, IL-1β, IL-6, IL-10, IL-18 and TNF6." (PMID 38191855, 2024). "Furthermore, the baseline excessive pro-inflammatory cytokines, such as TNF-α, IL-6, IL-1α, IL-1β, and IL-18, released after hepatic cell damage in NASH or further stage, might predispose NAFLD patients to cytokine storm in the setting of sepsis, resulting in worse outcomes." (PMID 39407795, 2024). "In fact, enrichment of the repressive mark H3K9me2 was increased in promoters of TNFA, IL-1B, CXCL8, and IL-17 at 1 dpb in patients that develop sepsis." (PMID 39768289, 2024). "In our study, taraxerone inhibited sepsis-induced increases in inflammatory cytokines like TNF-α, IL-1β, and IL-6." (PMID 39543653, 2024). "CLP-induced experimental sepsis resulted in a significant upregulation in the expression levels of TNF-α, IL-1β, IL-6, IL-10, ROS and MDA." (PMID 36608000, 2023).
Sepsis (continued). "In support of this clinical observation, the SARS-2-N protein aggravates lung injury and accelerates cell death in sepsis and acute lung inflammation mouse models by facilitating NLRP3 inflammasome assembly and promoting IL-1β production." (PMID 36936774, 2023). "Numerous anti-inflammatory immunomodulatory treatments have been used to combat the proinflammatory phase of sepsis; however, these immunomodulatory agents (TNF-α, IL-1β, toll-like receptor-4, etc.)have failed in clinical trials." (PMID 36816800, 2023). "In a mouse model of LPS-induced sepsis, mice fed a ketone monoester had reduced markers of NLRP3 activation and markers of hepatic inflammation, including Il-1β and Tnfα." (PMID 37113697, 2023). "Furthermore, the expression indicates that Neu_ Il1b exhibited a circulating phenotype of Neu with ICAMlowCxcr1high, but transformed to the reversely migrated Neu with ICAMhighCxcr1low under septic circumstances, suggesting the impairment of neutrophil migration in sepsis." (PMID 37808269, 2023). "According to the reviewed research articles, MIP-based biosensors can be applied for inflammation and sepsis biomarkers, such as human serum albumin, C-reactive protein, serum amyloid A, tumor necrosis factor-alpha (TNF-α), procalcitonin, IL-6, and IL-1β." (PMID 37366985, 2023). "In experimental CLP-induced sepsis, preconditioning of AD-MSCs with EPA led to a reduction of lung inflammation, edema and alveolar collapse, and levels of IL-1β, KC, and TGF-β, and increased VEGF levels and improved lung function." (PMID 37007034, 2023). "Namely, LPS-induced inflammation and/ or sepsis results in the activation of both TNF-α and IL-1β, but these cytokines initiate different pathways’ cascades that cooperate in the induced effect, even though they are distinctively different." (PMID 38136765, 2023). "Sepsis up-regulates both NLRP3 and IL-1β expression in whole muscle, ultimately leading to elevated concentrations of circulating IL-1β." (PMID 37447158, 2023). "We observed a significant reduction in IL-1-β, IL-6, and TNF-α pro-inflammatory cytokines with betaine treatment in sepsis-induced rats, in line with the studies in the literature." (PMID 37970921, 2023). "Further research was conducted to reveal the associations between m6A patterns and inflammatory factors, including interleukin (IL)-1β, IL-8, IL-10, IL-11 and TNF receptor superfamily member 1A (TNFRSF1A), in sepsis." (PMID 36781867, 2023). "Since sepsis is usually accompanied by VEC dysfunction, and proinflammatory cytokines IL-1β, IL-6 and TNF-α are important in the occurrence and development of sepsis, we first examined if E2 can affect release of inflammatory cytokines from HUVEC." (PMID 37265700, 2023). "Statistically significant elevations in IL-6, IL1-β, TNF-α, and ANG-2 levels were found in the FIP sepsis induction group compared to the normal group." (PMID 37255096, 2023). "The serum levels of pro-inflammatory cytokines IL-1β, IL-6, and TNF-α were significantly increased after sepsis, and down-regulated by inhibiting MAPK14 to 56.7%, 64.8%, and 72.6% compared with the sepsis group, respectively." (PMID 37180171, 2023). "In our sepsis model, the serum levels of three major inflammatory cytokines, TNF-α, IL-6, and IL-1β, were drastically elevated at 12 h of induction." (PMID 36675101, 2023). "During endotoxin tolerance in sepsis, histone deacetylase SIRT1 accumulates on the IL-1β and TNF-α promoters, and NAD+ levels are elevated, resulting in enhanced H3K16 deacetylation." (PMID 36774341, 2023). "Elevated levels of TLR2 in multiple organs of old mice augment the expression of cardiodepressant cytokines TNF-α, IL-1β, IL-6 and MCP-1 during sepsis, leading to greater cardiac dysfunction and high mortality." (PMID 38094127, 2023).